VRK2 (VRK serine/threonine kinase 2)
Diseases named in the same sentence as VRK2 in open-access papers (continued):
Sharing a sentence is not in itself a finding about the gene and the disease.
cancer (13 papers, 2013 to 2025). A tumor composed of atypical neoplastic, often pleomorphic cells that invade other tissues. "VRK2 is often highly expressed in various types of cancers and is involved in cancer pathogenesis, but the underlying mechanisms remain unclear." (PMID 37653031, 2023). "Both VRK1 and VRK2 proteins have been associated with the proliferation phenotype in carcinomas." (PMID 24079673, 2013). "We also demonstrated that the level of RNF144A is increased in response to the stress and further downregulates VRK2 through proteasomal degradation in various types of cancer cells." (PMID 40204710, 2025). "The results showed that the frequency of c.499 = A, which leads to translation of the more active 167I VRK2, was higher in cancer tissue." (PMID 38186576, 2023). "VRK2, as an active kinase, plays a role in the regulation of cancer cell invasion through the NFAT pathway and COX-2 expression." (PMID 37653031, 2023). "We conclude that VRK2 promoter methylation is observable among cancer subtypes and is a predictor for VRK2 expression and thus a VRK1 dependency." (PMID 36040810, 2022). "Taken together, these studies suggest that targeting VRK1 in cancers that harbor VRK2 promoter–methylated is a potential therapeutic strategy." (PMID 36040810, 2022). "In summary, by integrating genome-wide, loss-of-function genetic screens with RNA sequencing and DNA methylation, we identified VRK1 as a selective vulnerability in CNS and PNS cancers with low VRK2 expression." (PMID 36040810, 2022). "VRK2 is most highly expressed in cells undergoing division, and is therefore present in notable amounts in some cancer cells." (PMID 35911672, 2022). "DACT1, VRK2, MELTF, and FGF12 have been implicated in cancers other than CC, and PRICKLE2 has been reported to correlate with CC." (PMID 32408396, 2020). "Given the roles of autophagy in the pathogenesis of human cancer, the current study provides a novel insight into the oncogenic activity of VRK2–Akt complexes in the lysosomes via modulation of autophagy." (PMID 29872222, 2018). "Previous studies have reported that a somatic VRK2 mutation was not related to cancer progression, and rs1051061 has not been reported as a cancer-related SNP." (PMID 38186576, 2023). "Previous studies showed that VRK2 regulates cancer proliferation." (PMID 38186576, 2023). "Therefore, we compared sequence differences between VRK2 mRNA isolated from normal tissue and cancer tissue." (PMID 38186576, 2023). "Recently, several studies have shown how vaccinia-related kinase 2 (VRK2) is related to cancer." (PMID 38186576, 2023). "The RNA level of VRK2 was higher in cancer tissues than in normal tissues." (PMID 38186576, 2023). "To identify genes or pathways that predict VRK1 dependency, we correlated gene expression data from the Cancer Cell Line Encyclopedia (CCLE) with VRK1 dependency and found that it was most strongly correlated with the loss of expression of its paralog VRK2 (Pearson correlation = 0.37, q < 10–25)." (PMID 36040810, 2022). "Similarly, pediatric and adult gliomas and neuroblastomas require either VRK1 or VRK2, which have overlapping but essential pro-survival function in these cancers." (PMID 35911672, 2022). "Also, it would be critical to confirm whether inhibiting the activity of the upstream enzyme could actually reduce the change from V form to I form of VRK2, as it could determine the possibility of the enzymes as the anti-cancer therapeutic." (PMID 38186576, 2023). "Interestingly, we found that mTOR increased VRK2 expression in cancer cells." (PMID 37653031, 2023). "Thus, we detected the level of Ki-67, which is a proliferation index, to figure out whether VRK2 affects the cancer proliferation." (PMID 38186576, 2023). "The literature discussed here was obtained from a search of the published literature and ClinicalTrials.gov with the following key terms: checkpoint inhibition, cancer immunotherapy, PD-1, PD-L1, SHP2, PTPN2, ITK, VRK2, CDK4/6, GSK-3, and PAG." (PMID 35911672, 2022).
cancer (continued). "SHP2, ITK, VRK2, PTPN2, GSK-3, CDK4/6, and PAG all have evidence supporting their relationship to the PD-1 pathway in T cells and pro-tumorigenic role in cancer cells." (PMID 35911672, 2022). "The present study supports the paradigm that lysosomal VRK2 serves as a functional regulator of autophagy via the recruitment of activated Akt to lysosomes to control the proper biogenesis of functional lysosomes, which could be a novel molecular target for cancer therapy." (PMID 29872222, 2018).
neurological disorders (4 papers, 2016 to 2023). "Additionally, variation of the gene encoding a second BAF kinase, VRK2, is associated with several neurological disorders." (PMID 36980188, 2023).
psychiatric disorder (4 papers, 2020 to 2026). A disorder characterized by behavioral and/or psychological abnormalities, often accompanied by physical symptoms. "Previous studies have revealed that patients with psychiatric disorders had a higher mRNA expression level of vaccinia-related kinase 2 (VRK2) than did healthy individuals." (PMID 36810050, 2023). "Since future studies on Vrk2 gene function will be needed to explore the genetic basis of psychiatric disease, an understanding of gene structure is a necessary first step." (PMID 32583282, 2020). "Most previous studies of VRK2 expression have focussed on proliferating cells, despite the emerging importance of VRK2 for the aetiology of psychiatric disease." (PMID 32583282, 2020).
neurodegenerative disease (1 paper, 2016). A disorder of the central nervous system characterized by gradual and progressive loss of neural tissue and neurologic function. "Therefore, genetic variations could affect expression of the VRK2 gene, and malfunctions in VRK2 kinase activity might contribute to susceptibility to neurodegenerative diseases." (PMID 27377031, 2016).
neurodevelopmental disorder (1 paper, 2026). A behavioral and cognitive disorder with onset during the developmental period that involves impaired or aberrant development of intellectual, motor, or social functions. "Together, they reveal a glia–glia signaling axis in which microglial VRK2‐dependent cytokine signaling regulates astrocytic metabolism to sustain tonic inhibition in the MD thalamus—a mechanism potentially underlying thalamocortical dysfunction in VRK2‐associated neurodevelopmental disorders." (PMID 41263186, 2026).
VRK2 also shares sentences with these, for which no sentence is quoted: genetic generalized epilepsy (3 papers); bipolar disorder (2); focal epilepsies (2); neuroblastoma (2); adenocarcinoma (1); alcohol use disorder (1); Alzheimer disease (1); amyotrophic lateral sclerosis (1); autism spectrum disorder (1); dentatorubral-pallidoluysian atrophy (1); developmental delay (1); ependymoma (1); Epileptic encephalopathy (1); Hypertension (1); infection (1); insomnia (1); liver cancer (1); lung carcinoma (1); metabolic disease (1); mood disorder (1); Obesity (1); post-traumatic stress disorder (1); prostate adenocarcinoma (1); Stroke (1); uterine carcinosarcoma (1).